TTR (transthyretin)
Diseases named in the same sentence as TTR in open-access papers (continued):
Sharing a sentence is not in itself a finding about the gene and the disease.
malnutrition (continued). "Biomarkers for malnutrition (albumin and transthyretin) and inflammation (CRP and α1-acid glycoprotein) were significantly associated with mortality in older men." (PMID 30249038, 2018). "Transthyretin assay method is a relatively cheap, easy, and sensitive method that can be used to assess malnutrition." (PMID 28932602, 2017). "Transthyretin is considered as a good marker for prognosis of malnutrition and monitoring refeeding efficacy and its assay serves as a key step in the assessment of nutritional status." (PMID 28932602, 2017). "Transthyretin and albumin were used as biochemical markers of malnutrition to evaluate the prevalence and to categorize control group and study group into moderate, severe, and normal." (PMID 28932602, 2017). "Patients with these malnutrition-associated characteristics (any deficiency, MUST ≥ 1, and/or abnormal transthyretin levels) displayed a higher degree of dysbiosis compared to the other subjects." (PMID 27894337, 2016). "We investigated malnutrition by laboratory markers including P-transthyretin, and anthropometric data using the MUST." (PMID 27894337, 2016). "TTR is synthesized mainly in hepatic tissue, therefore, a decrease in plasma TTR was reported in cases of severe liver diseases, malnutrition and acute inflammation." (PMID 24586698, 2014). "Both CP and PaCa patients suffer from malnutrition and cachexia stimulating the synthesis of acute-phase proteins in the liver but the synthesis of apolipoproteins, transthyretin, and retinol-binding protein drops." (PMID 24349355, 2013). "TTR plasma levels have thus been used as sensitive biochemical parameters of subclinical malnutrition, as both the adequacy of protein as well as energy intakes are reflected in its plasma levels." (PMID 23844025, 2013). "Healthy serum TTR ranges from 3 to 8 μM, with lower levels indicating potential malnutrition." (PMID 39982986, 2025). "Thus, although TTR is useful in identifying malnutrition, even in the presence of chronic inflammation, when related to acute illness, values should be interpreted with caution." (PMID 39125329, 2024). "Thus, TTR levels can be helpful in evaluating and diagnosing a malnutrition status, but it is important to consider the involvement of inflammatory processes to interpret TTR levels correctly." (PMID 36009453, 2022). "Taken together, the data indicate that malnutrition and inflammation may similarly suppress the production of TTR through distinct and unrelated pathophysiological mechanisms while operating in concert to downsize LBM stores." (PMID 35943703, 2022). "Therefore, a starvation diet/malnutrition would likely result in reduction of serum TTR levels due to both reduced TTR synthesis and increased TTR uptake and catabolism." (PMID 31316837, 2019). "Therefore, serum transthyretin can be used as a good and dependable marker to assess acute malnutrition among children admitted to hospitals." (PMID 28932602, 2017). "In addition, PDAC patients often experience malnutrition, lowering the levels of TTR, which is involved in energy intake, acute/chronic disease states, nutritional status, and inflammatory processes." (PMID 29190982, 2017). "Therefore, the implementation of serum transthyretin level measurement in conjunction with anthropometric measurement for diagnosis of malnutrition in Ethiopian hospitals is highly recommended." (PMID 28932602, 2017). "Interestingly, in humans transthyretin is used to indicate malnutrition, and it is plausible that nesting marine turtles have decreased concentrations of this protein due to fasting." (PMID 27293623, 2014). "TTR is used in clinical practice as a marker in several conditions, such as predicting outcome for critically ill patients, in Alzheimer's disease, amyloidosis, inflammation and malnutrition." (PMID 19383125, 2009). "TTR from the liver is a marker of malnutrition and inflammatory processes." (PMID 19383125, 2009).
malnutrition (continued). "Therefore, TTR serum levels can be used as a sensitive biochemical parameter of subclinical malnutrition, since both the synthesis of proteins as well as energy intake are reflected in its serum levels." (PMID 19662213, 2007). "In light of the cited study results, it could be hypothesized that the transthyretin levels in IBD patients should rather be considered as an early marker of malnutrition, strongly correlated with the dietary protein intake and short-term changes in the patient’s body composition." (PMID 37571416, 2023). "Despite the lower energy intake with respect to the recommended intake, the mean serum transthyretin level was approximately 30.0 mg/dL, indicating that energy restriction (about 25 kcal/kg/day) does not cause clinically overt malnutrition in tube-fed patients with SMID in this study." (PMID 37960177, 2023). "Thus, hemoglobin may be a useful indicator of long-term malnutrition and transthyretin (half-life, 2 days) as a beneficial indicator of short-term malnutrition, at least in the outpatients enrolled in the study." (PMID 35971083, 2022). "The decrease in TTR levels in CKD may be due to malnutrition and/or infectious disease." (PMID 18752671, 2008). "Since malnutrition is the most common symptom observed in MAP infected animals, we believe that a transthyretin based screening test can be used to identify and monitor progression of JD infection in animals." (PMID 19424492, 2009). "Transthyretin (TTR) which exists in various isoforms, is a valid marker for acute phase response and subclinical malnutrition." (PMID 19662213, 2007). "Thus, a TLISA biosensor for TTR would provide an inexpensive, equipment-free, and potentially globally impactful POC assay for malnutrition." (PMID 39982986, 2025). "Transthyretin (TTR) rapidly responds to adequate protein intake/infusion, which could be used as a marker to identify malnutrition." (PMID 39125329, 2024). "Thereby, malnutrition, characterized by gradual LBM downsizing and reductions in body stores of essential amino acids like methionine, can impede LBM protein synthesis and accretion, diminishing the TTR neuroprotective activities." (PMID 39273520, 2024). "On the other hand, lower levels of TTR were observed during malnutrition or inflammation as a negative acute-phase reactant." (PMID 34572310, 2021). "The difference in physical appearance between study group and control group, identified by MUAC and transthyretin measurements, suggests that it is possible to identify malnutrition in children easily without invasive procedures." (PMID 28932602, 2017). "Assays for albumin, prealbumin (or transthyretin), transferrin and retinol binding proteins can be used as biological markers for malnutrition in patients with no ongoing inflammatory condition (option)." (PMID 12915908, 2003). "During the inflammatory process, these proteins may be low due to inflammation rather than malnutrition, since the liver prioritizes the synthesis of acute phase proteins (CRPs), consequently reducing the synthesis of albumin and TTR." (PMID 39519615, 2024). "Indeed, as a typical negative acute-phase plasma protein, the TTR gene in the liver is downregulated after trauma, inflammation, or malnutrition resulting in a marked decrease in circulating protein levels." (PMID 36009453, 2022). "In patients with mild to moderate malnutrition receiving ENEFLUID® for 12 weeks as IDPN, serum TTR was not improved, decreases in protein intake was mitigated, no adverse events occurred." (PMID 39666754, 2024). "In patients with mild to moderate malnutrition receiving ENEFLUID® as IDPN for 12 weeks during maintenance hemodialysis, serum TTR, a mortality predictor for patients on hemodialysis, was not increased; however, decrease in protein intake was mitigated, and no adverse events were observed." (PMID 39666754, 2024).
carpal tunnel syndrome (38 papers, 2013 to 2025). Entrapment of the median nerve in the wrist that is characterized by numbness, tingling and painful movement. "This is a multisystem disorder caused by mutations of the transthyretin protein and is associated not only with cardiac diseases or carpal tunnel syndrome but also with nerve, liver, lung, gastrointestinal tract, kidney, or eye pathologies." (PMID 36837536, 2023). "Biopsy confirmation of ATTR deposition in patients with bilateral carpal tunnel syndrome with V122I TTR mutation may be possible in a future study with long term follow up as well." (PMID 35959393, 2022). "For note, distal enlargement of median nerves was also observed in our study, which might associate with carpal tunnel syndrome in these TTR-FAP patients." (PMID 33716932, 2021). "The TTR V142I homozygote was >65 years and female, with a diagnosis of HF or arrhythmia plus spinal stenosis, bilateral carpal tunnel syndrome, multi/chronic diarrhea, eye disease, and lower extremity numbness." (PMID 38541013, 2024). "Echocardiography and cardiac magnetic resonance, along with the history of bilateral carpal tunnel syndrome, were suspicious for TTR-CA." (PMID 33121442, 2020). "Also, bilateral carpal tunnel syndrome (CTS; 10 patients, 71%), associated with unexplained weight loss, gastrointestinal disturbances, and autonomic dysfunction (nine patients, 64%), were the most recurring “red flags” among TTR‐mutated patients." (PMID 37725003, 2024). "TTR can also deposit in the flexor tenosynovium resulting in carpal tunnel syndrome (CTS)." (PMID 34017661, 2021). "It should be noted that many patients with TTR-FAP are erroneously diagnosed with simple carpal tunnel syndrome; progressive symptoms or lack of improvement after carpal tunnel release surgery often leads to the correct diagnosis." (PMID 23425518, 2013). "Carpal tunnel syndrome is an early but nonspecific manifestation of TTR-FAP." (PMID 23425518, 2013).
ovarian carcinoma (37 papers, 2005 to 2025). A malignant neoplasm originating from the surface ovarian epithelium. "The OVA1-test, for example, combines five proteins (Apolipoprotein A1, Beta 2 microglobulin, MUCIN-16, Transferrin and Prealbumin/Transthyretin) and is used to divide women into groups with high, intermediate, or low risk of ovarian cancer." (PMID 39981201, 2025). "The subsequent multivariate index assay is OVA1, which combines serum biomarkers CA125, transthyretin, transferrin, beta-2 microglobulin, and apolipoprotein A-1 to calculate a risk score for ovarian cancer." (PMID 38275400, 2024). "OVA1 is an FDA-approved blood test that measures the levels of five proteins (CA125, transferrin, transthyretin, apolipoprotein A1, and beta-2 microglobulin) to detect ovarian cancer risk in women." (PMID 36232415, 2022). "A truncated variant of TTR has been described as a biomarker for ovarian cancer, indicating a close interplay between nutritional status, inflammation and possibly the occurrence of cancer." (PMID 23844025, 2013). "TTR formerly called prealbumin, has previously been identified as a potential early diagnostic marker for ovarian cancer and known as a marker for acute-phase inflammatory response and nutritional status." (PMID 23268721, 2012). "The aim of this study was to evaluate multiplexed bead-based immunoassay of multiple ovarian cancer-associated biomarkers such as transthyretin and apolipoprotein A1, together with CA125, to improve the identification and evaluation of prognosis of ovarian cancer." (PMID 22970327, 2012). "Recently, a new truncated variant of TTR together with apolipoprotein A1 and a cleaved fragment of inter-α-trypsin inhibitor heavy chain H4 were described as an efficient set of new biomarkers for ovarian cancer in women." (PMID 16225703, 2005). "Serum TTR is traditionally a valid marker for nutritional status in general and in cancer patients it has gained considerable interest with regard to the use as an early diagnostic marker in ovarian cancer." (PMID 16225703, 2005). "It shows promising potential as a biomarker for early detection of ovarian cancer—especially when used alongside TTR and TF." (PMID 40927964, 2025). "Studies show TTR offers higher sensitivity than CA‐125 in early‐stage ovarian cancer, suggesting its potential as a complementary biomarker for early detection." (PMID 40927964, 2025). "The combination of HE4, creatinine, carcinoembryonic antigen (CEA), and transthyretin (TTR) had 93.7% sensitivity and 70.6% specificity in predicting ovarian cancer compared to benign tumors." (PMID 38275400, 2024). "TTR levels have been found to be reduced in the serum of patients with ovarian cancer and advanced cervical and endometrial cancer." (PMID 37238197, 2023). "Transthyretin (TTR) is another potential biomarker that is downregulated in ovarian cancer patients." (PMID 36233339, 2022). "The combination of CA125, transferrin, TTR and ApoA1, using a proteomic analysis, yielded a sensitivity of 89% at a specificity of 92% for the early detection of ovarian cancer." (PMID 33800113, 2021). "TTR was found to be an important marker for the detection of stage I–II ovarian cancer, with a sensitivity and specificity of 78.6% and 68.8%, respectively." (PMID 33800113, 2021). "Low TTR serum levels were found in ovarian cancer and used with other biomarkers to detect ovarian cancer." (PMID 33800113, 2021). "We found that Transthyretin was downregulated while Clusterin was upregulated in the plasma of chemotherapy-resistant ovarian cancer patients." (PMID 30917846, 2019). "The final results show that the logistic regression gives high performance for both tasks, and HE4-ELISA, PDGF-AA, Prolactin, TTR is the best biomarker combination for detecting ovarian cancer." (PMID 30396341, 2018). "Consistently, plasma apoA-I levels were included in a FDA-approved test for early stage ovarian cancer, together with transthyretin, transferrin, β2-microglobulin and CA12540." (PMID 29396407, 2018).
ovarian carcinoma (continued). "The second test approved by the FDA, OVA1TM Ovarian Triage Test, combines a panel of five biomarkers for ovarian cancer (CA-125, transthyretin, apolipoprotein A1, ß2-microglobulin, and transferrin) identified through serum proteomics using SELDI-TOF-MS." (PMID 28837575, 2017). "When CA125 was combined with the biomarkers (transthyretin and apolipoprotein A1), the overall sensitivity and specificity for discriminating between ovarian cancer and healthy individuals were significantly improved in the ROC curve." (PMID 22970327, 2012). "While transthyretin and apolipoprotein A1 have been used several times as potential biomarkers of ovarian cancer, the three-biomarker panel was newly evaluated using our Korean population." (PMID 22970327, 2012). "Many acute phase proteins such as haptoglobin and transthyretin have also been recently characterized as ovarian cancer biomarkers for early detection." (PMID 23251472, 2012). "The serum levels of CA125 was significantly higher in ovarian cancer patients than that in healthy individuals and benign patients, while the levels of transthyretin and apolipoprotein A1 were lower in ovarian cancer patients." (PMID 22970327, 2012). "The three biomarkers (CA125, TTR, and Apo-A1) significantly distinguished patients with early stage ovarian cancer from healthy individuals." (PMID 22970327, 2012). "The serum level of full-length transthyretin was down-regulated among patients with later stage ovarian cancer relative to that in healthy controls and patients with colorectal, breast, or prostate cancer." (PMID 22970327, 2012). "Data from another study with a four-marker panel (CA125, apolipoprotein A-1, transthyretin, and transferrin) reported a sensitivity and specificity of 96% and 98%, respectively, for early-stage ovarian cancer." (PMID 21577260, 2011). "Markers such as interleukins 6 and 8, lysophosphatidic acid, eosinophil-derived neurotoxin and COOH-osteopontin fragments, apolipoprotein A1, and transthyretin have mostly noted large increases in sensitivity and specificity in several forms of ovarian cancer." (PMID 21577260, 2011). "It is interesting that our work identified the m/z 13797 peak corresponding to the 13.9 kDa marker, which we identified as the complete TTR protein product to be down-regulated in early ovarian cancer." (PMID 19662218, 2007). "More strikingly, the sensitivity in distinguishing normal versus mucinous early stage ovarian cancer, utilizing apoA-1, TF and TTR (CA125 excluded), was 95% (specificity 86%; AUC 95%)." (PMID 19662218, 2007). "It is interesting that our work identified the m/z 13797 peak corresponding to the 13.9 kDa marker, which we identified as the complete TTR protein product to be differentially expressed as down-regulated in early ovarian cancer." (PMID 19662218, 2007). "The main aim of the study was therefore to characterize differences in microheterogeneity between ascitic fluid and plasma of women affected with ovarian cancer and to evaluate the tumor site as the possible source of TTR." (PMID 16225703, 2005). "The results of the present study confirm previous results for cancer patients in general and especially for patients with ovarian cancer, regarding the greatly reduced serum levels of TTR and RBP." (PMID 16225703, 2005). "A truncated form of TTR has recently been described to be part of a set of biomarkers for the diagnosis of ovarian cancer." (PMID 16225703, 2005). "Nothing however is known with regard to ovarian cancer as a source of TTR itself or cleavage products thereof." (PMID 16225703, 2005). "In order to assess the expression of TTR within ovarian cancer tissue we performed immunohistochemical staining using a polyclonal TTR antibody in paraffin embedded sections." (PMID 16225703, 2005). "In ovarian cancer tissues diffuse TTR immunostaining was only observed within blood vessels, haemorrhages or plasma insudations." (PMID 16225703, 2005).